AKAP12 (A-kinase anchoring protein 12)
Diseases named in the same sentence as AKAP12 in open-access papers (continued):
Sharing a sentence is not in itself a finding about the gene and the disease.
myocardial infarction (1 paper, 2022). Gross necrosis of the myocardium, as a result of interruption of the blood supply to the area, as in coronary thrombosis. "As a result, AKAP12 and GLRA2 may have a role in the progression of myocardial infarction by affecting cardiac contractility." (PMID 36499335, 2022).
oral squamous cell carcinoma (1 paper, 2022). "Moreover, miR-103a-3p regulates proliferation and apoptosis by targeting RCAN1 in oral squamous cell carcinoma (OSCC) cells, miR-103 promotes HCC growth by inhibiting AKAP12 or by promoting glucose metabolism function, and miR-103 promotes metastasis and EMT by inhibiting LATS2." (PMID 36273122, 2022).
osteoarthritis (1 paper, 2022). A noninflammatory degenerative joint disease occurring chiefly in older persons, characterized by degeneration of the articular cartilage, hypertrophy of bone at the margins and changes in the synovial membrane. "So far A kinase anchoring protein-12 (AKAP12) and RNF11 have not shown any abnormal expression in any osteoarthritis and rheumatoid arthritis." (PMID 36238643, 2022).
ovarian serous tumor (1 paper, 2023). A benign, borderline, or malignant epithelial tumor of the ovary characterized by the presence of neoplastic epithelial cells that, in well differentiated tumors, resemble the epithelial cells of the fallopian tube and, in poorly differentiated tumors, show anaplastic features. "The validation experiments showed that the mRNA of PER1, AKAP12, and MMP17 was highly expressed in normal ovarian epithelial cells compared to SOC cell lines and there was a positive correlation between protein levels of PER1, AKAP12 and MMP17 and metastasis in human ovarian serous tumors." (PMID 37434173, 2023).
pancreatic cancer (1 paper, 2023). "AKAP12 was among the genes that are potentially involved in tumor–stroma talk in pancreatic cancer." (PMID 37296997, 2023).
retinal (1 paper, 2022). "The previous study has reported that AKAP12 could induce the formation of the blood-retinal barrier (BRB) via barriergenesis in developing human eyes, and defects in these mechanisms contributed to the disappearance of tight junction proteins, thereby leading to retinal pathologies such as RB." (PMID 36110213, 2022).
sarcoma (1 paper, 2022). A usually aggressive malignant neoplasm of the soft tissue or bone. "We found that missense mutation of AKAP12 was the primary type of genetic alteration and the N1461Mfs*26/Kfs*2 alteration, a truncation mutation, was detected in one case of sarcoma (SARC), one case of STAD, one case of UCEC, and two cases of COAD." (PMID 36110213, 2022).
steatosis (1 paper, 2025). Increased lipid within the cytoplasm of cells. "The goal of this work is to examine how AKAP12's PKA-anchoring ability regulates outcomes of alcohol-associated steatosis." (PMID 40199859, 2025). "In conclusion, the AKAP12-PKA scaffold controls lipogenic signaling, disruption of which favors steatosis during ALD." (PMID 40199859, 2025).
urothelial carcinoma (1 paper, 2023). A malignant neoplasm derived from the transitional epithelium of the urinary tract (urinary bladder, ureter, urethra, or renal pelvis). "Among genes recorded in “Pathology” section in THPA, staining intensities of AKR1B1, TCHH, AKAP12, and IGF2 are distinctly higher in tissues from urothelial carcinoma than in normal bladder." (PMID 36512456, 2023).
uterine corpus endometrial carcinoma (1 paper, 2022). A endometrial carcinoma (disease) that involves the body of uterus. "According to our analysis, the highest alteration frequency of AKAP12 appeared for Uterine Corpus Endometrial Carcinoma (UCEC) cases with “mutation” as the predominant type." (PMID 36110213, 2022).
vascular occlusive diseases (1 paper, 2011). "Finally, mouse and human vascular occlusive diseases were associated with reduced AKAP12 expression." (PMID 21483686, 2011).
tumor (72 papers, 2009 to 2025). "Several hypoxia genes with high-frequency somatic mutations were identified, including CDKN1A, PPARGC1A, and AKAP12, which showed unequivocal associations with tumor initiation." (PMID 38806990, 2025). "These cells are readily transformed by single oncogenes such as Src or Ras, suggesting that the loss of AKAP12's tumor suppressor function renders the cell transformation-prone." (PMID 22811901, 2012). "Reexpression of AKAP12 in MAT-LyLu cells causes a small decrease in primary subcutaneous tumor growth yet severely suppresses the formation of macroscopic lung metastasis." (PMID 22811901, 2012). "We stratified cancer patients into high-and low-AKAP12 expression groups according to medium expression value, and subsequently, TCGA and GEO datasets were utilized to explore the association between AKAP12 expression and the prognosis of distinct tumor patients." (PMID 36110213, 2022). "We next investigate whether AKAP12 expression and copy number alterations were associated with tumor immune infiltration based on TIMER database." (PMID 36148016, 2022). "Meanwhile, the expression of MYH9, FN1, LTBP1, CALR and AKAP12 is effective in discriminating HR-NB from LR-NB patients, indicating that these non-invasive biomarkers may be used to detect patients at risk of developing aggressive tumor phenotypes." (PMID 37947594, 2023). "The a-kinase anchoring protein 12 (AKAP12) has tumor inhibitory activity, studies showed that its hypermethylation can significantly distinguish EAC from ESCC and normal esophagus, AUC of 0.943, showing high differential diagnosis ability (P < 0.0001)." (PMID 40718833, 2025). "Studies had found that AKAP12 was lowly expressed in many cancers and had anti-tumor activity, such as esophageal squamous carcinoma cell and breast cancer." (PMID 40226362, 2025). "AKAP12 overexpression significantly reduced tumor volume and weight, while this effect was partially abolished by TCF21 knockdown." (PMID 40226362, 2025). "Knockdown of AKAP12 reduced tumor sphere formation, impaired cell migration, and enhanced cisplatin sensitivity." (PMID 40567611, 2025). "Recent research demonstrated that miR-183-5p can increase HCC cell proliferation by suppressing the expression of tumor suppressors (including AKAP12, DYRK2, FOXN3, FOXO1 and LATS2) which is agreement with our results." (PMID 37168369, 2023). "AKAP12 was found to be downregulated in almost 50% of CRC tissues as compared with their matched non-tumor tissues." (PMID 38304289, 2023). "The m6A level of AKAP12 was significantly down-regulated in the tumor by 8.88-fold and conversely that of TRIM2 was significantly up-regulated by 2.38-fold." (PMID 36303829, 2022). "The regulatory effect of AKAP12 as a tumor suppressor gene in tumors has been extensively studied and confirmed." (PMID 36148016, 2022). "As for the tumors lacking normal tissues in the TCGA repository, we further evaluated the expression differences of AKAP12 between tumor and normal tissues through the GTEx database." (PMID 36110213, 2022). "A further two-group analysis between CR and nCR also demonstrated the overexpression of proteins that play a tumor-suppressive role, including AKAP12, DCTN3, and SELENOH, in the CR group." (PMID 36361712, 2022). "We further investigated the roles of AKAP12 in tumor functional status through the CancerSEA website." (PMID 36110213, 2022). "Thereupon, we examined alteration in AKAP12 phosphorylation between primary tumor versus normal tissues." (PMID 36110213, 2022). "Our analysis strongly showed that AKAP12 played a vital role in the immune infiltration of various cancer types, especially for tumor-promoting CAFs." (PMID 36110213, 2022). "For this purpose, TISIDB, an integrated repository portal for tumor-immune system interactions, was used to analyze the relations between immunomodulators and AKAP12 expression." (PMID 36148016, 2022).
tumor (continued). "In conclusion, our study provides strong evidence that AKAP12 is closely related to tumor immunity in STAD from three aspects: immune infiltration cells, immune pathways, and immunomodulators." (PMID 36148016, 2022). "The genetic alteration profiling of AKAP12 in different tumor samples within the TCGA cohorts was explored." (PMID 36110213, 2022). "A kinase anchor protein 12 (AKAP12) as a tumor suppressor in various cancers has been extensively studied and confirmed." (PMID 36148016, 2022). "Consistently, AKAP12 involved in tumor metastasis was induced in cisplatin-resistant NSCLC H460 cells." (PMID 36110213, 2022). "In contrast, tumor malignant biological behaviors were enhanced by interfering with the expression of AKAP12." (PMID 36148016, 2022). "It is essential to investigate the precise tumor-promoting or -suppressing immune cells to clarify the specific role of AKAP12-related immune cells." (PMID 36148016, 2022). "A-kinase anchor protein 12 (AKAP12) exerts anti-tumor effects by acting as a scaffolding protein in signal transduction." (PMID 36300115, 2022). "The heatmap visualized the significant relationship between AKAP12 expression with distinct tumor states." (PMID 36110213, 2022). "Pathway enrichment volcano map showed that significantly enriched pathways of AKAP12-related immunomodulators include some immune and tumor-related pathways." (PMID 36148016, 2022). "On the one hand, AKAP12 is recognized as a tumor suppressor, whose diminished expression in cancer cells is accompanied by an enhanced invasive and metastatic phenotype." (PMID 36110213, 2022). "The depletion of HDAC7 in HUVEC results in the overexpression of A-kinase anchor protein 12 (AKAP12), which is a tumor/angiogenesis suppressor gene responsible for the inhibition of migration and tube formation." (PMID 33996829, 2021). "As expected, many DMGs that were hypermethylated and downregulated in CMT including TP63, LIFR, PLA2G16, LRIG1, STAT5A, and AKAP12 and have been known as tumor suppressors, were identified from high scoring (OncoScore > 50) CMT-DMRs." (PMID 32693820, 2020). "Low AKAP12 expression in a larger cohort of patients characterized tumor invasiveness, recurrence, and progression, indicating its potential as a prognostic biomarker." (PMID 29391485, 2018). "Although our results indicate AKAP12 downregulation leads to tumor aggressiveness, purposely increasing AKAP12 expression as a therapy should be considered with caution." (PMID 29391485, 2018). "AKAP12, a tumor suppressor target of miR-186-5p, was upregulated in PC-3 and MDA-PCa-2b cells transfected with a miR-186-5p inhibitor." (PMID 29653561, 2018). "SSeCKS/AKAP12 expression in microenvironmental cells (non-tumor cell autonomous) also controls metastatic progression." (PMID 30323895, 2018). "Kaplan Meier curve shows that low AKAP12 values correlated with tumor recurrence/progression (p = 0.001), independent of WHO grade." (PMID 29391485, 2018). "Among the established miR-186-5p targets, we selected AKAP12 for further evaluation due to its central role in cell proliferation, colony formation, cell invasion and epithelial mesenchymal transition and tumor growth." (PMID 29653561, 2018). "Studies also suggested AKAP12 to be a tumor suppressor and angiogenesis suppressor gene that down-regulates vascular endothelial growth factor, potentially through epigenetic regulation." (PMID 29137139, 2017). "SSeCKS/Gravin/AKAP12 (SSeCKS) is a kinase scaffolding protein known to suppress metastasis by attenuating tumor-intrinsic PKC- and Src-mediated signaling pathways." (PMID 29050279, 2017). "The current study presents evidence that SSeCKS/AKAP12 suppresses metastasis in the peritoneum by modulating key signaling mediators that control secretion of tumor chemoattractants." (PMID 29050279, 2017). "The expression and activity of AKAP12 is proposed to be affected by the hypoxic tumor microenvironment." (PMID 29137139, 2017).
tumor (continued). "The levels of A kinase anchor protein 12 (AKAP12), which exerts tumor suppressor activity, were significantly lower in Tg tumors than in normal Tg lung tissues (P < 0.05)." (PMID 25909170, 2015). "AKAP12 is a scaffold protein in signal transduction with tumor suppressor activities, and present in the plasma membrane, cytosol or endoplasmic reticulum." (PMID 24727804, 2014). "In our tumor validation set we focused on AKAP12, DCBLD2, NT5E with a higher stringent threshold cut-off, and SPON1 whose expression appears to be highly cancer-related in the explorative “training series”." (PMID 24133572, 2013). "AKAP12 also acts as a tumor suppressor which regulates cell-cycle progression and inhibits Src-mediated oncogenic signaling and cytoskeletal pathways." (PMID 22811901, 2012). "AKAP12 (aka SSeCKS and Gravin) has demonstrable growth suppressive properties and is down-regulated in a variety of human neoplasms supporting the idea that AKAP12 is a bonafide tumor suppressor gene." (PMID 21483686, 2011). "Because AKAP12 inhibits LoVo cell growth in vitro, we further assessed its effect on tumor formation in vivo." (PMID 21918680, 2011). "We also evaluated the expression of AKAP12 and cleaved-caspase-3 level in the tumor tissues of LoVo-CON or LoVo-AKAP12 group." (PMID 21918680, 2011). "The growth suppressive activities of AKAP12, together with its attenuated expression in both transformed cell lines and a variety of human neoplasms, have led to the concept of AKAP12 being a tumor suppressor gene." (PMID 21483686, 2011). "Nude mice injected with LoVo-AKAP12 cells had both significantly reduced tumor volume (p<0.01) and increased apoptosis compared to mice given AKAP12-CON." (PMID 21918680, 2011). "In HT1080 cells, AKAP12 was found to suppress tumor cell viability by inducing apoptosis via caspase-3 and was associated with a decreased expression of Bcl-2 and increased expression of Bax." (PMID 21918680, 2011). "AKAP12/Gravin (A kinase anchor protein 12) is one of the A-kinase scaffold proteins and a potential tumor suppressor gene in human primary cancers." (PMID 21918680, 2011). "As shown by both the WST assay and FACS analysis, AKAP12 displays tumor-suppressive activity in vitro." (PMID 21918680, 2011). "AKAP12 has tumor suppressor properties and is indeed one of the only tumor suppressors known to be induced by retinoids." (PMID 23554628, 2010). "Functionally, AKAP12 knockdown markedly impaired tumor sphere-formation." (PMID 40567611, 2025). "However, the positive cells of TCF21, AKAP12, and metastasis marker E-cadherin were reduced, while proliferation marker Ki67-positive cells were enhanced in the tumor tissues of the AKAP12 + sh-TCF21 group." (PMID 40226362, 2025). "Taken together, our study revealed a novel mechanism of AKAP12 as a tumor suppressor in LUSC." (PMID 40226362, 2025). "Besides, the GEPIA database revealed that AKAP12 was lowly expressed in LUSC tumor tissues compared to normal tissues." (PMID 40226362, 2025). "AKAP12 may also affect cell proliferation, migration, and tumor metastasis in LUSC through other pathways, but these mechanisms require further research to clarify in the future." (PMID 40226362, 2025). "In conclusion, AKAP12 might be a tumor suppressor in LUSC, which was mediated by TCF21 and could inhibit cell growth, metastasis, and glycolysis to restrain LUSC malignant progression." (PMID 40226362, 2025). "As a known tumor suppressor, AKAP12 inhibits the growth and metastasis of cancer cells." (PMID 40943642, 2025). "RT‐PCR showed that AKAP12 was downregulated in tumour tissues." (PMID 37795791, 2023). "In the present study, we systematically analyzed the immune significance of the tumor suppressor AKAP12 from various aspects including immune infiltration cells, immune-related pathways, and immunomodulators and constructed an AKAP12-related immunomodulator prognostic signature." (PMID 36148016, 2022).
tumor (continued). "Its decreased expression and low activity in tumor cells may be due to hypermethylation in the promoter region of AKAP12 gene and are closely related to the malignancy degree." (PMID 36148016, 2022). "Secondly, GSEA enrichment analysis in our study showed that antigen processing and presentation are activated in patients with AKAP12 high expression, which has been proved to be an important and essential link in the process of immune cells killing cancer antigens in tumor immunity." (PMID 36148016, 2022). "In summary, we detected that AKAP12 expression was reduced in most tumor types." (PMID 36110213, 2022). "Moreover, the tumor suppressor effects of AKAP12 were also noted in certain cancer types such as BRCA and LIHC." (PMID 36110213, 2022). "As a tumor suppressor, AKAP12 mRNA and protein levels were downregulated in STAD patients." (PMID 36148016, 2022). "In addition to its inhibitory effect on tumor growth and metastasis by scaffolding key regulatory proteins such as protein kinase C, F-actin, and cyclins, AKAP12 also exerts important role in the drug resistance mechanism of tumors." (PMID 36148016, 2022). "AKAP12 is a scaffold protein that plays a tumor-suppressive role in most cancers, but may also exert context-dependent protumorigenic functions." (PMID 36077674, 2022). "Silencing of AKAP12 might decrease the infiltration of tumor-promoting CAFs, thus improving anti-VEGF therapy sensitivity." (PMID 36110213, 2022). "Moreover, the vitro and vivo experiments have confirmed that overexpression of AKAP12 significantly inhibits tumor cell proliferation and metastasis by controlling oncogenic signaling pathways in a spatiotemporal manner." (PMID 36148016, 2022). "While AKAP12 was significantly higher in normal tissues than in tumor tissues." (PMID 35756646, 2022). "AKAP12, another ERK1/2 inhibitor, was found preferentially upregulated in FGFR tumors, whereas RALT/ERRFI1, an EGFR inhibitor and degradation promoter, was strongly overexpressed only in the F2T2↑ tumor, explaining its paradoxical EGFR expression loss." (PMID 33853673, 2021). "AKAP12 has been investigated as a tumor suppressant in some human primary cancers, including GC; however, in the present study, we found it significantly over-expressed in the TMEsubtype-H high-risk group, suggesting an increased risk of OS with higher expression levels." (PMID 34771544, 2021). "Of the differentially expressed genes, IFI6, SLC39A9 and ZNF185 showed a strong correlation with tumor progression and patient survival in the OncoLnc database while roles for AKAP12 and DUSP5 in carcinogenesis and poor prognosis have previously been established for other cancer types." (PMID 32849815, 2020). "Based on this, AKAP12 has been suggested to have a tumor suppressing function." (PMID 29433456, 2018). "Compared with the control group, PRKARIA and AKAP12 were lower in the tumor-stroma crosstalk." (PMID 30519576, 2018). "Moreover, our data also showed that PRL-3 can stimulate certain tumor suppressor genes, such as A-Kinase anchor protein 12 (AKAP12)." (PMID 26967563, 2016). "The anti-tumor activity of AKAP12 was evaluated in a primary xenograft model using nude mice." (PMID 21918680, 2011). "AKAP12-mediated suppression of tumor growth may be achieved through direct or indirect interaction with multiple apoptotic proteins and associated signaling pathways in cancer cells." (PMID 21918680, 2011). "However, the roles of AKAP12 in various tumor types are to be elucidated." (PMID 36110213, 2022).